MAGEF1 (MAGE family member F1)
Description:
Enhances ubiquitin ligase activity of RING-type zinc finger-containing E3 ubiquitin ligases. Proposed to act through recruitment and/or stabilization of the E2 ubiquitin-conjugating enzyme at the E3:substrate complex. MAGEF1-NSMCE1 ubiquitin ligase complex promotes proteasomal degradation of MMS19, a key component of the cytosolic iron-sulfur protein assembly (CIA) machinery. Down-regulation of MMS19 impairs the activity of several DNA repair and metabolism enzymes such as ERCC2/XPD, FANCJ, RTEL1 and POLD1 that require iron-sulfur clusters as cofactors. May negatively regulate genome integrity by inhibiting homologous recombination-mediated double-strand break DNA repair.
Synonyms: MAGE-F1
Tractability: PROTAC: ubiquitination databases record sites on it.
Gene: Protein-coding gene on chromosome 3 (184,710,364 to 184,712,064, reverse strand). Ensembl gene ENSG00000177383.
Subcellular location (Human Protein Atlas): Actin filaments
Gene Ontology:
Molecular function: protein binding
Biological process: negative regulation of double-strand break repair via homologous recombination; protein ubiquitination; ubiquitin-dependent protein catabolic process; negative regulation of transcription by RNA polymerase II
Cellular component: nucleus
Genetic constraint (gnomAD): Missense variants: 322 observed, 306.6 expected, observed/expected ratio (o/e) 1.05, 90% interval 0.96 to 1.15. Synonymous variants: 115 observed, 130.04 expected, observed/expected ratio (o/e) 0.88, 90% interval 0.76 to 1.03.
Homologues: Orthologues: chimpanzee MAGEF1 (99% identical), macaque MAGEF1 (87% identical), dog MAGEF1 (86% identical), pig MAGEF1 (85% identical), zebrafish ndnl2 (30% identical), Drosophila melanogaster MAGE (18% identical). Paralogues in human: MAGED2 (43% identical), NSMCE3 (42% identical), MAGED1 (39% identical), MAGEL2 (39% identical), MAGEE1 (38% identical), TRO (37% identical), MAGED4 (35% identical), MAGED4B (35% identical), NDN (34% identical), MAGEB16 (33% identical), MAGEB18 (33% identical), MAGEB2 (32% identical), and 25 more.
Diseases named in the same sentence as MAGEF1 in open-access papers:
MAGEF1 is named in the same sentence as 6 diseases in open-access papers, as found by Europe PMC text mining. Sharing a sentence is not in itself a finding about the gene and the disease. The quoted sentences say what the papers report.
cancer (1 paper, 2022). A tumor composed of atypical neoplastic, often pleomorphic cells that invade other tissues. "And MAGEF1 was highly amplified in multiple human cancer types and related with increased mutational burden." (PMID 35558067, 2022).
MAGEF1 also shares sentences with these, for which no sentence is quoted: colon cancer (1 paper); glioma (1); head and neck cancer (1); head and neck squamous cell carcinoma (1); tumor (1).